WNT5A (Wnt family member 5A)
Diseases named in the same sentence as WNT5A in open-access papers (continued):
Sharing a sentence is not in itself a finding about the gene and the disease.
Insulin resistance (19 papers, 2013 to 2024). Increased resistance towards insulin, that is, diminished effectiveness of insulin in reducing blood glucose levels. "Wnt member 5a (Wnt5a) and secreted frizzled-related protein 5 (Sfrp5) are proinflammatory proteins associated with insulin resistance and chronic low-grade adipose tissue inflammation." (PMID 32491086, 2020). "The cited authors found that lower serum SFRP5 potentiated the association between Wnt-5A and insulin resistance." (PMID 30704061, 2019). "Obese people with “unhealthy adipocytes” with reduced expression of Sfrp5 and high Wnt5a have an associated insulin resistance with a high risk of cardiovascular complications." (PMID 29564334, 2018). "Notably, LPS or TNF-α treatment also upregulated Wnt5a expression in adipocytes, indicating that adipocyte-derived Wnt5a is also implicated in adipose tissue inflammation and insulin resistance." (PMID 27608847, 2016). "Adipose tissue inflammation triggers macrophage activation and insulin resistance because of the over-activation of the WNT5A." (PMID 37542207, 2023). "In this prospect, reports have suggested the involvement of Wnt5a in endothelial dysfunction, especially in relation to insulin resistance." (PMID 34371968, 2021). "Circulating Wnt5a correlated strongly with insulin resistance and hepatic enzymes (SGOT, SGPT), particularly in children with lower circulating Sfrp5 concentrations." (PMID 34371968, 2021). "Similar results were observed in whole body Wnt5a knockout mice, which showed that Wnt5a ablation attenuated high-fat/high-sucrose (HFHS)-induced insulin resistance, and these mice displayed decreased expression of TNF-α, CCL2, and IL-6 in adipose tissue." (PMID 27608847, 2016). "Wnt5a is widely expressed in adipose tissues, and the deleterious role of Wnt5a through activating the non‐canonical Wnt pathway in the development of inflammation and insulin resistance has been clearly revealed." (PMID 34042263, 2021). "Maternal inulin intervention may improve glucose intolerance and insulin resistance resulting from maternal HF diet exposure by modifying DNA methylation of Wnt5a and Pi3k in the liver." (PMID 32116778, 2020). "It has been reported that Wnt5a, which is a pro-inflammatory cytokine, promotes insulin resistance." (PMID 32491086, 2020). "Accordingly, Wnt5a ablation in obese mice ameliorates insulin resistance." (PMID 29564334, 2018). "In details, the animal studies revealed that the activation of JNK-1 by WNT5A impairs the activity of a target protein called insulin receptor substrate-1 (IRS-1) leading to suppressed insulin signaling and development of insulin resistance." (PMID 34184187, 2021). "These inflammatory responses enhanced Wnt5a to activate c-Jun N-terminal kinase (JNK) cascade and resulted in the progression of insulin resistance." (PMID 31470850, 2019). "Overactivation of Wnt5a/PCP pathway is also detected in ECs from patients with T2DM, thus inhibiting this signalling could ameliorate insulin resistance and dysfunction of ECs from T2DM patients." (PMID 34042263, 2021). "WNT5A, a non-canonical WNT ligand, has been shown to promote adipose tissue inflammation and insulin resistance in animal studies." (PMID 29229927, 2017).
non-small cell lung carcinoma (19 papers, 2010 to 2025). A group of at least three distinct histological types of lung cancer, including non-small cell squamous cell carcinoma, adenocarcinoma, and large cell carcinoma. "WNT-5A expression is highly increased in non-small cell lung cancer (NSCLC) and has been associated with poor prognosis." (PMID 26514730, 2016). "In a research on non-small-cell lung cancer, it was shown that the growth, movement, and invasion capabilities of cancerous cells were hindered when Wnt5a was suppressed by microRNA." (PMID 40373156, 2025). "Wnt5a was overexpressed in tumor samples and associated with EMT and VM in epithelial ovarian cancer and non-small-cell lung cancer (NSCLC)." (PMID 34476217, 2021). "For instance, it was described that the enforced expression of Wnt5a promoted epithelial-to-mesenchymal transition and metastasis in non-small-cell lung cancer." (PMID 33987473, 2020). "In the articles “Dickkopf-1-promoted vasculogenic mimicry in non-small cell lung cancer is associated with EMT and development of a cancer stem-like cell phenotype” and “Overexpression of Wnt5a promotes angiogenesis in NSCLC,” intracellular glycoprotein inclusions are visible in the tissue sections." (PMID 40786517, 2025). "A recent study indicated that high Wnt5a expression is associated with poor prognosis in non-small-cell lung cancer (NSCLC) patients; however, the underlying mechanism was not clear yet." (PMID 29054966, 2017). "Wnt5a is overexpressed during the progression of human non-small cell lung cancer." (PMID 23349696, 2013). "ATF-2 activated the Wnt/Ca2+ pathway and promoted the expression of Wnt5a, Wnt11, CaMKII and NLK, which regulated the proliferation and invasion of non-small cell lung cancer cells, suggesting that Ca signaling is directly involved in malignant behavior of tumor cells." (PMID 39687904, 2024). "In this regard our data is somewhat different from those reported from analyses of non-small cell lung cancer where Wnt5a did not correlate with VEGF expression in the cancer tissue but with VEGF in the surrounding stromal tissue." (PMID 22039506, 2011).
osteoarthritis (19 papers, 2016 to 2026). A noninflammatory degenerative joint disease occurring chiefly in older persons, characterized by degeneration of the articular cartilage, hypertrophy of bone at the margins and changes in the synovial membrane. "The observed discrepancy between GEO dataset findings, which indicate the down-regulation of WNT5A/B mRNA in osteoarthritis (OA), and IHC results showing unchanged protein levels is likely due to tissue heterogeneity and compartmentalization." (PMID 40299569, 2025). "Wnt5a, which regulates the activities of osteoblasts and osteoclasts, is reportedly overexpressed in osteoarthritis (OA) tissues." (PMID 38645498, 2024). "WNT5A expression was increased in the synovial fluids of patients with spondyloarthropathy compared to those with osteoarthritis." (PMID 35055107, 2022). "Among Wnt proteins, Wnt-5a, a representative ligand that activates the β-catenin independent pathway in Wnt signaling, is involved in the pathogenesis of osteoarthritis (OA)." (PMID 31513634, 2019). "In the present study, we found that the accumulation of β-catenin and Wnt5a increased in IL-1β-induced osteoarthritis chondrocytes, and expression of the downstream transcription factor, RUNX2, was also increased." (PMID 31888697, 2019). "Wnt5a is increased in the synovium in patients with RA and osteoarthritis (OA), and inhibition of Wnt5a is reported to block the activation of cultured synovial fibroblasts from RA patients." (PMID 28724439, 2017). "In addition, WNT5A expression was increased in osteoclasts in the damaged PsA joints compared to that in those from osteoarthritis." (PMID 35055107, 2022). "Similarly, WNT5A gene silencing promoted mineralization in human osteoblasts obtained from osteoarthritis patients." (PMID 35534526, 2022). "WNT5A is known to be involved in the pathogenesis of osteoarthritis." (PMID 30257711, 2018). "This study aimed to identify the optimal extracorporeal shock wave (ESW) intensity and to investigate its effect on subchondral bone rebuilt in vivo and Wnt5a/Ca2+ signaling in vitro using an osteoarthritis (OA) rat model and bone marrow mesenchymal stem cells (BMMSCs), respectively." (PMID 29164146, 2017). "Our research aims to investigate the expression of WNT Family Member 5A/B (WNT5A/B), β-catenin, acetyl-α-tubulin, Dishevelled-1 (DVL-1), and Inversin (INV) in the synovial membrane of osteoarthritis (OA) hips." (PMID 40299569, 2025). "The results showed increased numbers of WNT5A+ and CD68+ expressing osteoclasts in the joints of the PsA patients compared to those of the osteoarthritis patients (p < 0.01)." (PMID 35055107, 2022). "Wnt-5a played a crucial role in the atypical Wnt/PCP and Wnt/PKC pathways of osteoarthritis osteoblasts." (PMID 35155643, 2021). "They found that Wnt5a, a classical non-canonical Wnt pathway activator, has a five-fold over-expression in osteoarthritis osteoblasts." (PMID 31546898, 2019). "Therefore, we investigated the difference of CD68+WNT5A+ osteoclasts in the destructive joints of PsA and non-inflammatory arthritis (osteoarthritis)." (PMID 35055107, 2022).
breast tumors (18 papers, 2010 to 2023). "The blockade of TIM-3 in breast tumor explants downregulated genes related to cancer pathways, including those associated with tumor cell proliferation/migration/invasion (WNT5A, LIF, XDH2, SNAI, CDH2, ADAMST12, PLAU, and CDK14)." (PMID 32616706, 2020). "High levels of secreted Wnt5a were detected in patient serum, and enhanced serum Wnt5a was positively correlated with microvessel density in breast tumors." (PMID 33754039, 2021). "The loss of WNT5A is associated with early relapse in invasive ductal breast carcinomas and short recurrence-free survival, supporting WNT5A as a candidate breast tumor suppressor." (PMID 24586797, 2014). "If this can be explained by the fact that patients with Wnt-5a expressing breast tumors already have a very favorable prognosis remains to be investigated." (PMID 23990917, 2013). "Since the patients in the study were given adjuvant treatment with TAM or no adjuvant treatment it was possible to compare the effect of TAM in patients with ER+ breast tumors expressing either low levels (−/+) or high (++/+++) levels of the Wnt-5a protein." (PMID 23990917, 2013). "On the other hand, Wnt5a is frequently upregulated in breast tumors in comparison with surrounding tissues and was shown to promote the invasion of MCF7 cells via the JNK pathway." (PMID 20507565, 2010). "The elucidation of reciprocal interactions of breast CAFs with endothelial cells may inspire the development of conceptually novel targeted therapeutics with the aim of thwarting the FOSL2/Wnt5a axis of breast tumor angiogenesis." (PMID 33754039, 2021). "Additionally, it has been shown that early breast tumors and pre-neoplastic lesions express WNT5A protein that decreases in late-stage tumors and lung metastases." (PMID 30171384, 2018). "Additionally, we have also demonstrated that WNT5A expression can be used as a potential prognostic biomarker in pre-menopausal patients with ER+ breast tumors." (PMID 27623766, 2016). "In contrast, Wnt-5a was not a prognostic factor in premenopausal ER- breast tumors." (PMID 23990917, 2013).
hepatocellular carcinoma (16 papers, 2009 to 2026). A malignant tumor that arises from hepatocytes. "Regarding the role played by gene mutations, changes in Hbx modulate the expression of Wnt-5a in hepatoma cells, whereas inactivating mutations in APC, AXIN1 and AXIN2 genes or methylation in APC aberrantly modify the Wnt signaling response." (PMID 37512809, 2023). "Previous studies have suggested that mutations in the X protein of HBV regulate Wnt5a expression in hepatocellular carcinoma (HCC) tissues and an HCC cell line." (PMID 38062395, 2023). "A novel pathway activated by Wnt5a has been shown to induce EMT in cell lines derived from late-stage mesenchymal-type hepatocellular carcinomas (HCC) and cancers of the breast, lung, and colon." (PMID 27571105, 2016). "Similarly, low to undetectable levels of Wnt5a are present in hepatocellular carcinoma (HCC) and normal liver tissues, whereas strong immunostaining was seen in chronic hepatitis, cirrhosis, and dysplastic liver cells." (PMID 24156409, 2013). "The migration and invasion of hepatoma cells could be regulated through the Wnt5a pathway." (PMID 36147503, 2022). "Even though recent evidence suggests that WNT5a might also activate canonical signaling in a PCP‐independent and tissue‐dependent manner, WNT5a is known to repress TCF‐mediated WNT signaling, e.g., in hepatocellular carcinoma cells." (PMID 40165582, 2025). "Next, analysis of Wnt/β-catenin signaling components revealed that mRNA expression levels of Wnt5A, CTNNB1P1, DVL1, SMAD4, and JUN were detected in well-differentiated hepatoma but not in their para-carcinoma tissues." (PMID 32273945, 2020).
neuroblastoma (15 papers, 2009 to 2025). Neuroblastoma (NB) is the most common solid, extracranial childhood tumor. "High WNT5A levels are associated with low-risk neuroblastoma." (PMID 31569501, 2019). "Considering that Ten-3 expression has also been linked to reduced neuroblastoma malignancy, we hypothesize that Wnt3a/Wnt5a-mediated Ten-3 expression might be associated with the Wnt3a/Wnt5a context-dependent protective effects against neuroblastoma." (PMID 31156379, 2019). "In contrast, transcriptome analyses show that high expression of WNT3A or WNT5A correlates with longer survival, while high WNT3 expression level indicates higher risk of neuroblastoma." (PMID 31569501, 2019). "Xenograft experiments showed that the expression level of WNT5A is higher in human IGR-N-91 neuroblastoma cells than control grafted cells." (PMID 31569501, 2019). "Metastatic neuroblasts in a xenograft model displayed lower Wnt5a expression than the primary neuroblastoma cells." (PMID 22655072, 2012). "However, in terms of autocrine signals WNT3 and WNT5A were the most highly expressed Wnt ligands across all five neuroblastoma cell lines." (PMID 27531891, 2016). "Finally, we show that expression of these two WNT5A isoforms is altered in breast and cervix carcinomas, as well as in the most aggressive neuroblastoma tumors." (PMID 24260410, 2013).
chronic lymphocytic leukemia (14 papers, 2016 to 2025). "MiR-15/16 also repressed the expression of ROR1, a receptor for Wnt5a that promotes cell proliferation in leukemia and anoncoembryonic protein expressed in chronic lymphocytic leukemia (CLL) cells, as miR-15/16 expression is inversely related to ROR1 levels." (PMID 38675388, 2024). "Chronic lymphocytic leukemia (CLL) is characterized by the accumulation of neoplastic B lymphocytes with high levels of Wnt5a in the plasma." (PMID 35210425, 2022). "Patients with chronic lymphocytic leukemia (CLL) have high plasma-levels of Wnt5a, which can induce phosphorylation of ERK1/2 and enhance CLL-cell proliferation." (PMID 33097837, 2021). "It has been reported that DOCK2 gene is overexpressed in chronic lymphocytic leukemia B-cells promoting their proliferation in response to Wnt5a." (PMID 30753220, 2019). "Wnt5a has been demonstrated to activate NF-κB pathway-dependent survival signalling in chronic lymphocytic leukaemia cells." (PMID 29531296, 2018). "Furthermore, Wnt5a can induce proliferation in chronic lymphocytic leukemia (CLL) cells through a distinct mechanism." (PMID 27571105, 2016). "In chronic lymphocytic leukemia (CLL), WNT5A was shown to be secreted from nurse-like cells (NLC) in the CLL microenvironment in the bone marrow and secondary lymphoid tissues." (PMID 36982422, 2023). "Chronic lymphocytic leukemia (CCL) cells are induced to migrate by Wnt5a in a chemokine gradient manner, which is important in regulating chemotaxis and trans-endothelial migration of CLL cells, apparently through upregulating PCP components including Vangl2, Prickle1, CK1ε, Dvl, and Celsr1." (PMID 27571105, 2016).
nasopharyngeal carcinoma (14 papers, 2008 to 2026). A carcinoma arising from the nasopharyngeal epithelium. "Dysregulation of the WNT5A signaling has been implicated in the increased migration and invasiveness of cancer cell lines and the metastatic potential of gastric, breast and nasopharyngeal cancers." (PMID 33178184, 2020). "Wnt5A plays a dual role in cancer, acting as a tumor promoter in some cancers, such as ovarian and nasopharyngeal cancers, by inducing EMT and cell migration, while acting as a tumor suppressor in others, like gastric and CRC, by inhibiting EMT." (PMID 41545904, 2026). "We confirmed the regulatory efficiency of Beclin1 shRNA in control and Wnt5a overexpressed nasopharyngeal carcinoma cell lines by WB." (PMID 35517407, 2022). "To verify the role of WNT5a protein in nasopharyngeal carcinoma radiation resistance, we supplemented exogenous WNT5a protein." (PMID 35517407, 2022). "We have demonstrated that Wnt5a can reduce the radiation sensitivity of nasopharyngeal carcinoma in vitro and in vitro experiments." (PMID 35517407, 2022). "Meanwhile, we found much more greater autophagosomes in overexpressed-Wnt5A nasopharyngeal carcinoma cells by electron microscopy." (PMID 35517407, 2022). "By studying Wnt5A-mediated protective autophagy in promoting radiation resistance in nasopharyngeal carcinoma cells, we hope that the Wnt5A and Beclin1 can become effective targets for overcoming radiation resistance in the future." (PMID 35517407, 2022). "To explore the effect of Wnt5A on radiation sensitivity in nasopharyngeal carcinoma cell lines (6-10B and CNE-2), we constructed stable cell lines with overexpression of Wnt5A." (PMID 35517407, 2022). "WNT5A, was found to promote cancer cell proliferation and enhance cell migration in nasopharyngeal cancer." (PMID 33928018, 2020). "Regarding the involvement in cancer, overexpression of WNT5A significantly induced migration and invasion whereas WNT5A knockdown decreased them in cell lines from nasopharyngeal cancer." (PMID 33178184, 2020). "WNT5A mRNA was also elevated in hepatic metastases from nasopharyngeal cancer and was correlated with poor survival." (PMID 27571105, 2016). "Both CNE2 and 6-10B with exogenous supplementation of WNT5a protein showed increased cell viability at radiation doses with 4 and 6Gy, which may indicate that WNT5a protein promotes radiation resistance of nasopharyngeal carcinoma in vitro." (PMID 35517407, 2022). "Our research further uses transmission electron microscopy to detect autophagosomes in Wnt5a-overexpressed nasopharyngeal carcinoma cells and controls, we found that autophagosomes significantly increased size and number in Wnt5a-overexpressed cells relative to controls." (PMID 35517407, 2022). "Wnt5a was also shown to up-regulate stem-like cell markers in nasopharyngeal carcinoma." (PMID 27571105, 2016). "Wnt5a also promoted EMT in nasopharyngeal cancers through activation of PKC and induction of Snail." (PMID 27571105, 2016). "The experimental results proved that WNT5A expression could reduce the radiosensitivity of nasopharyngeal carcinoma, and knockdown of Beclin1 which is a main target of WNT5A partially reduced WNT5A-mediated protective autophagy in promoting radiation resistance." (PMID 39253139, 2024). "Stable knockdown of Wnt5a in S18 nasopharyngeal carcinoma cells significantly decreased the percentage of CD24−/CD44+ stem-like cells, while over-expression of Wnt5a in S26 nasopharyngeal carcinoma cells S26 significantly increased the percentage of CD24−/CD44+ cells." (PMID 27571105, 2016). "In this study, we found that radioactive rays could significantly promote the expression of Wnt noncanonical signaling pathways ligands in nasopharyngeal carcinoma, among which Wnt5A was the most markedly altered." (PMID 35517407, 2022).
nasopharyngeal carcinoma (continued). "They found that Wnt5a promoted epithelial-mesenchymal transition (EMT) in nasopharyngeal carcinoma (NPC) cells and induced the accumulation of CD24-CD44+ cells and side population, suggesting that Wnt5a is an important molecule in promoting stem cell characteristics in this cancer type." (PMID 36969011, 2023). "In vitro and in vivo studies on the radiation resistance model in nasopharyngeal carcinoma, we found that radiation can induce the overexpression of Wnt canonical signaling pathways (represented by Wnt3a) and Wnt non-canonical signaling pathways (represented by Wnt5A)." (PMID 35517407, 2022).